SLC2A2 (solute carrier family 2 member 2)
Diseases named in the same sentence as SLC2A2 in open-access papers (continued):
Sharing a sentence is not in itself a finding about the gene and the disease.
tumor (36 papers, 2002 to 2025). "There were also expression differences between the two primary tumours in ~ 50 insulin/glucose-related genes, such as SLC2A2, which encodes the GLUT2 glucose transporter and PIK3R1, involved in the metabolic actions of insulin." (PMID 40438247, 2025). "Both glucose uptake and the expression of the glucose transporter Glut1 (Slc2a1), but not that of Glut2 (Slc2a2), Glut3 (Slc2a3), or Glut4 (Slc2a4), were elevated in Cpt1a-deficient ErbB2 tumor cells." (PMID 39097623, 2024). "However, the expression levels of SLC2A2 tend to be significantly higher in tumor cells in contrast to the normal tissue." (PMID 22412968, 2012). "The results showed that SLC2A2 was overexpressed in adjacent normal tissues, while the other three genes were upregulated in HCC tumor tissues." (PMID 40269756, 2025). "According to data from the UALCAN database, LUAD patients’ tumor tissues had hypomethylation of SLC2A1, SLC2A2, SLC2A5, SLC2A6, SLC2A7, SLC2A11 and hypermethylation of SLC2A3, SLC2A10, and SLC2A14 compared to normal tissues." (PMID 36518662, 2022). "Tumor tissues with high c-Met expression level in TCGA have increased expression of H6PD, PDK2, PDK4, PDPR, PKLR, SLC2A2 genes whereas decreased expression of GYS1, HK1, HK2, SLC2A1, significantly." (PMID 34059694, 2021). "This cell line also mostly mimicked downregulated small molecule transporters seen in tumours, e.g. NPC1L1, SLC25A15/20, SLC2A2, SLC1A1 and SLC7A2." (PMID 30176945, 2018). "Targeting SLC2A2 may serve as a promising therapeutic strategy for liver-related diseases, particularly HCC, by addressing its dual role in differentiation and tumor progression." (PMID 40279337, 2025). "Further validation via another database revealed that 4 hub genes, ACAT1, SLC2A2, PCK1 and ABAT, were correlated with tumor survival of HCC in T2DM with HbA1c ≥ 6.5%, suggesting the prognostic prediction function of these 4 genes and even new therapeutic targets in HCC." (PMID 33865459, 2021). "Glucose transporters include SLC2A1, SLC2A2, SLC2A3, and SLC2A4, and we found the expression of SLC2A1 was significantly upregulated in HCC tumor, contrast with that in adjacent non-tumor tissues (from TCGA Database)." (PMID 37443106, 2023).
cancer (29 papers, 2002 to 2025). A tumor composed of atypical neoplastic, often pleomorphic cells that invade other tissues. "Moreover, a pan-cancer analysis of SLC2A family genes found SLC2A2 were associated with the prolonged OS of HCC." (PMID 40269756, 2025). "The high or specific expression of other glucose transporters such as GLUT2/SLC2A2, GLUT3/SLC2A3, GLUT12/SLC2A12 and the fructose transporter GLUT5/SLC2A5 has also been associated with various cancer types and specific cancer stages." (PMID 36770817, 2023). "Our analysis revealed a consistent decrease in SLC2A2 expression with increasing cancer stage." (PMID 40279337, 2025). "This reduction correlated with increased expression of stem cell markers, such as PROM1, CK19, DLK1, SALL4, and EPCAM, suggesting that low SLC2A2 levels may promote cancer stem cell traits, malignancy, and therapeutic resistance." (PMID 40279337, 2025). "To delineate SLC2A2 attributes in HCC, we investigated its expression dynamics across different cancer stages using the TCGA HCC dataset." (PMID 40279337, 2025).
infection (16 papers, 2014 to 2025). The state of being infected such as from the introduction of a foreign agent such as serum, vaccine, antigenic substance or organism. "Both Ad-PDA (n = 7) and Ad-PDB (n = 7) treatment induced comparable expression levels of β cell-related genes, including Slc2a2 and Pcsk2, 3 days after infection, but only in the PDA-transfer group were the expressions sustained for longer than 1 week." (PMID 25397325, 2014). "In addition, higher expression of solute carrier family genes (Slc13a1, Slc26a3, Slc2a2, Slc40a1, Slc5a1, and Slc6a19) was seen in the gastric tissue of Muc1−/− mice compared with WT at sham and 8 h infection." (PMID 32793510, 2020).
metabolic disorders (11 papers, 2013 to 2025). "Fanconi-Bickel syndrome (FBS) is a rare metabolic disorder caused by decreased glucose transporter 2 (GLUT2) function due to several known mutations in the SLC2A2 gene." (PMID 38605735, 2024).
cardiovascular disease (4 papers, 2013 to 2023). "The association between SLC2A2 rs8192675 and high-density lipoproteins suggests the polymorphism may play a role in influencing high-density lipoproteins and thus metabolic risk of cardiovascular disease." (PMID 23341889, 2013).
SLC2A2 also shares sentences with these, for which no sentence is quoted: Insulin resistance (80 papers); Hepatic steatosis (10); diabetic nephropathy (7); Hyperinsulinemia (7); colon cancer (4); glucose metabolism disorder (4); hyperthyroidism (4); Hypoinsulinemia (4); Nephropathy (4); gestational diabetes (3); hyperlipidemia (3); Hypertension (3); neuroblastoma (3); renal tubular acidosis (3); rickets (3); COVID-19 (2); dermatitis (2); Fanconi syndrome (2); gastric cancer (2); hepatic (2); lung carcinoma (2); non-alcoholic fatty liver disease (2); ovarian carcinoma (2); psoriasis (2); Renal cyst (2); renal Fanconi syndrome (2); Sepsis (2); adenoma (1); alopecia areata (1); atopic dermatitis (1).
A further 72 diseases each share a sentence with SLC2A2 in 1 paper.